SOCS7 (suppressor of cytokine signaling 7)
Description:
Substrate-recognition component of a cullin-5-RING E3 ubiquitin-protein ligase complex (ECS complex, also named CRL5 complex), which mediates the ubiquitination and subsequent proteasomal degradation of target proteins, such as DAB1 and IRS1. Specifically recognizes and binds phosphorylated proteins via its SH2 domain, promoting their ubiquitination (By similarity). The ECS(SOCS7) complex acts as a key regulator of reelin signaling by mediating ubiquitination and degradation of phosphorylated DAB1 in the cortical plate of the developing cerebral cortex, thereby regulating neuron positioning during cortex development (By similarity). Functions in insulin signaling and glucose homeostasis through IRS1 ubiquitination and subsequent proteasomal degradation. Also inhibits prolactin, growth hormone and leptin signaling by preventing STAT3 and STAT5 activation, sequestering them in the cytoplasm and reducing their binding to DNA.
Synonyms: NAP4; NCKAP4
Tractability: Antibody: UniProt places it where antibodies can reach, with medium confidence; its Gene Ontology location is reachable by antibodies, with medium confidence.
Gene: Protein-coding gene on chromosome 17 (38,351,844 to 38,405,593, forward strand). Ensembl gene ENSG00000274211.
Subcellular location: Cytoplasm; Nucleus; Cell membrane
Subcellular location (Human Protein Atlas): Cytosol
Gene Ontology:
Molecular function: protein binding; phosphorylation-dependent protein binding; SH3 domain binding; signaling adaptor activity; ubiquitin-like ligase-substrate adaptor activity
Biological process: insulin receptor signaling pathway; layer formation in cerebral cortex; proteasome-mediated ubiquitin-dependent protein catabolic process; regulation of neuron migration; intracellular signal transduction; protein ubiquitination
Cellular component: cytoplasm; nucleus; Cul5-RING ubiquitin ligase complex; plasma membrane
Genetic constraint (gnomAD): Loss-of-function variants: 16 observed, 47.86 expected, observed/expected ratio (o/e) 0.33, 90% interval 0.22 to 0.51. The upper end of that interval is the gene's LOEUF score, 0.51, which puts it in group 2 of 6, group 1 being the genes least tolerant of losing a copy. Missense variants: 617 observed, 721.04 expected, observed/expected ratio (o/e) 0.86, 90% interval 0.8 to 0.92. Synonymous variants: 356 observed, 300.42 expected, observed/expected ratio (o/e) 1.18, 90% interval 1.09 to 1.29.
Homologues: Orthologues: macaque SOCS7 (99% identical), dog SOCS7 (97% identical), pig SOCS7 (97% identical), rat Socs7 (97% identical), chimpanzee SOCS7 (90% identical), mouse Socs7 (88% identical), rabbit SOCS7 (86% identical), guinea pig SOCS7 (65% identical), tropical clawed frog socs7 (60% identical), zebrafish socs7 (56% identical), Drosophila melanogaster Socs16D (26% identical), Caenorhabditis elegans F39B2.5 (9% identical). Paralogues in human: SOCS6 (22% identical), SOCS5 (15% identical), SOCS4 (13% identical), CISH (11% identical), SOCS2 (9% identical), SOCS3 (9% identical), SOCS1 (7% identical).
Diseases named in the same sentence as SOCS7 in open-access papers:
SOCS7 is named in the same sentence as 29 diseases in open-access papers, as found by Europe PMC text mining. Sharing a sentence is not in itself a finding about the gene and the disease. The quoted sentences say what the papers report.
breast carcinoma (9 papers, 2010 to 2022). "Higher expression levels of SOCS1, SOCS3, SOCS4, and SOCS7 have all been reported to associate with better prognosis in human breast cancer." (PMID 33758600, 2021). "A statistically significant relationship has been found between SOCS7 expression and cancer; in this study, the results showed that SOCS7 expression is associated with determining early tumor stage and with better prognosis and clinical outcome in breast cancer." (PMID 36169255, 2022). "We report a unique regulatory role for SOCS7 in controlling the malignant behaviour of breast cancer lines MCF7 and MDA-MB-231 in vitro and the MCF7 tumour xenografts in vivo." (PMID 25162020, 2014). "These migration data showed an additive influence of HGF treatment and SOCS7 knockdown on the in vitro migration of both breast cancer lines." (PMID 25162020, 2014). "Only recently a tumour suppressing role was described for SOCS7 particularly in breast cancer, and this intriguing role is still under investigation." (PMID 25162020, 2014). "SOCS7 loss has resulted in the amplification of HGF/C-MET growth and migrational signalling in the two studied breast cancer cell lines, but pharmacological blockade of PLCγ-1 enzymatic activity has mitigated this amplified signalling." (PMID 25162020, 2014). "Similarly, SOCS7 was also demonstrated to negatively control the growth factor signaling in breast cancer cells and limit their growth and migration." (PMID 35624501, 2022). "Tumor suppressive effects of SOCS7 were reported in the prostate, colon, and breast cancer." (PMID 34439155, 2021). "Further data reported by our group demonstrated a favourable role for SOCS7 in breast cancer." (PMID 24757565, 2014). "In this study we hypothesised a regulatory role for SOCS7 in HGF/C-MET signalling in breast cancer based on its multiple interactions with intermediate molecules downstream of the C-MET receptor." (PMID 25162020, 2014). "Here, we report our observations of the effect of knocking down SOCS7 gene on the behaviour of breast cancer cells both in vitro and in vivo and to elucidate whether this involves HGF/C-MET pathway using the PLCγ-1 blocker U73122." (PMID 25162020, 2014). "SOCS7 was found to be expressed in both normal/benign breast tissue and breast cancer specimens." (PMID 20433750, 2010). "Previously, it was detected that SOCS7 is differentially expressed in benign and malignant breast tissues and has critical regulatory functions in insulin-like growth factor I- and hepatocyte growth factor-induced breast cancer, indicating its involvement in the pathogenesis of human cancers." (PMID 35624501, 2022). "Furthermore, higher SOCS7 expression may be a predictor of better disease-free survival and overall survival in breast cancer." (PMID 24757565, 2014). "We here aimed to observe the effect of SOCS7 knockdown on the behaviour of breast cancer both in vitro and in vivo and to investigate whether SOCS7 knockdown in breast cancer cells MCF7 (ER +ve) and MDA-MB-231 (ER −ve) can affect their in vitro growth and migrational responses when treated with HGF." (PMID 25162020, 2014). "SOCS7 expression was also higher among those who remained disease free compared to all other patients who developed any type of recurrence (local or distant) or died from breast cancer during the same follow up period [mean copy number 2110 vs. 372, 95% CI (40, 3436), p = 0.045]." (PMID 20433750, 2010). "Elevated SOCS7 mRNA levels were inversely correlated with TNM and tumor stages of breast cancer consistent with better disease-free survival and overall survival." (PMID 34439155, 2021). "An inverse relationship between SOCS7 mRNA expression and the TNM stage as well as the tumour grade of breast cancer was found." (PMID 24757565, 2014). "More data demonstrated an involvement of the SOCS7 in the negative control of IGF-I/PLCγ-1 signalling in MCF7 and MDA-MB-231 breast cancer cell lines, which consequently limit their growth and migrational functions." (PMID 24757565, 2014).
bladder cancer (6 papers, 2015 to 2025). "miR-145 targets SOCS7 and promotes interferon induction in bladder cancer cells and Hepatitis C virus (HCV)." (PMID 38792727, 2024). "This was supported by previous studies that found SOCS7 silencing promoted the nuclear translocation of STAT3 in bladder cancer cells." (PMID 39431622, 2024).
acute liver failure (3 papers, 2020 to 2023). Rapid deterioration of liver function causing encephalopathy and coagulopathy. "In acute liver failure, PTPN14 aggravates the NFkB signaling pathway by promoting SOCS7 degradation." (PMID 36898991, 2023). "In addition, we observed altered phosphorylation on PTPN14, which has recently been demonstrated to initiate cytokine storm and aggravate acute liver failure by interacting with and targeting SOCS7, a negative regulator of NF-κB signaling pathway to proteasomal degradation." (PMID 35011700, 2022).
renal fibrosis (3 papers, 2017 to 2024). A final common manifestation of a wide variety of chronic kidney diseases characterized by glomerulosclerosis and tubulointerstitial fibrosis. "With reference to the report that miR199a‐3p repressed SOCS7 expression resulting in STAT3 activation during human renal fibrosis, the luciferase reporter assays in the present study confirmed that miR‐199a‐3p directly binds to SOCS7." (PMID 39431622, 2024).
pancreatic cancer (2 papers, 2024). "Transfection with miR‐199a‐3p increased the proliferation, invasion, migration, and drug resistance of pancreatic cancer cells by downregulating SOCS7, increasing STAT3 phosphorylation, and upregulating SAA1 expression." (PMID 39431622, 2024). "In conclusion, our study highlights the role of CAAs in promoting pancreatic cancer progression through the secretion of miR‐199a‐3p‐enriched exosomes targeting the SOCS7/STAT3/SAA1 pathway." (PMID 39431622, 2024). "We confirmed that miR‐199a‐3p‐mediated SOCS7 silencing significantly enhanced STAT3 phosphorylation in three pancreatic cancer cell lines." (PMID 39431622, 2024). "miR‐199a‐3p in CAA‐derived exosomes contributes to the malignant transformation of pancreatic cancer via the SOCS7/STAT3/SAA1 pathway, suggesting its potential as a biomarker and therapeutic target for PDAC." (PMID 39431622, 2024). "In this study, we demonstrated that exosomal miR‐199a‐3p secreted from CAAs contributes to the malignant transformation of pancreatic cancer cells by promoting the expression of SAA1 via the miR‐199a‐3p/SOCS7/STAT3 pathway." (PMID 39431622, 2024). "We show its utility by generating a SOCS7-based KRAS degrader that inhibits mutant KRAS pancreatic cancer cells’ proliferation." (PMID 38746666, 2024). "We then investigated whether differences in the expression of components of the SOCS7 E3 ligase complex, including the biodegraders, could explain the discrepancies between pancreatic cancer cells and the other cell lines." (PMID 38746666, 2024). "However, in pancreatic cancer cells (MIA PaCa-2, PDAC087T), the degradation efficiency of the sdAb mutants-SOCS7 was linked to the affinity of the corresponding mutated sdAbs." (PMID 38746666, 2024). "In addition, a SOCS7-based biodegrader enabled the degradation of endogenous KRAS oncoprotein in pancreatic cancer cells, ultimately leading to the cells’ proliferation inhibition." (PMID 38746666, 2024). "To further validate the influence of miR‐199a‐3p on SOCS7 and SAA1 expression in pancreatic cancer cells, we transfected three pancreatic cancer cell lines (Panc‐1, PK‐1, and PK‐45H cells) with a miR‐199a‐3p mimic." (PMID 39431622, 2024). "Subsequently, exosomal miR‐199a‐3p secreted from CAAs and taken up by surrounding pancreatic cancer cells suppressed SOCS7 expression, leading to STAT3 activation and increased SAA1 expression, ultimately resulting in a more aggressive phenotype in pancreatic cancer cells." (PMID 39431622, 2024). "Finally, we leverage these properties to construct a SOCS7-based KRAS degrader, that reduces RAS-dependent signaling and impedes the proliferation of pancreatic cancer cells." (PMID 38746666, 2024).
colon carcinoma (1 paper, 2022). "The current study aimed to investigate the effect of valproic acid (VPA) on SOCS-1, SOCS-2, SOCS-3, SOCS-5, SOCS6, and SOCS-7 gene expression and cell growth inhibition in colon carcinoma IS1, IS2, and IS3 cell lines." (PMID 35611249, 2022). "The results of the current study demonstrate that VPA plays its role through the upregulation of SOCS-1, SOCS-2, SOCS-3, SOCS-5, SOCS6, and SOCS-7 genes, resulting in cell growth inhibition and apoptosis induction in colon carcinoma IS1, IS2, and IS3 cell lines." (PMID 35611249, 2022).
colonic cancer (1 paper, 2014). "Similar to SOCS1 and SHP1, STAT6high HT-29 cells expressed low constitutive mRNA of SOCS3 and SOCS7 than STAT6null colonic cancer Caco-2 cells." (PMID 24757565, 2014). "Furthermore, in colonic cancer cell line HT-29 that constitutively expresses STAT6, there is downregulation of CIS and SOCS7 (in addition to SOCS1, SOCS3, and SHP1)." (PMID 24757565, 2014).
diabetic nephropathy (1 paper, 2017).
Hydrocephalus (1 paper, 2020). Hydrocephalus is an active distension of the ventricular system of the brain resulting from inadequate passage of CSF from its point of production within the cerebral ventricles to its point of absorption into the systemic circulation. "Amongst these, the SH3YL1 gene (related to cellular migration) and the SOCS7 gene (related to hydrocephalus in mice) are involved in CNS development." (PMID 32879369, 2020).
hypoglycaemia (1 paper, 2024). "The authors identified that SOCS7-/- mice display prolonged hypoglycaemia and lower glucose levels during insulin tolerance tests – many of the defects in SOCS7-deficient mice can be explained by enhanced inclusion action in SOCS7KO cells and increased IRS levels." (PMID 39676878, 2024).
IgA nephropathy (1 paper, 2017).
inflammatory skin disease (1 paper, 2022). Inflammatory skin disorders covers a broad category that includes many conditions ranging in severity, from mild itching to grave medical health complications These disorders are common in people of all ages and races. "Significantly, demonstrated that the lack of SOCS7 results in an inflammatory skin disease and that SOCS7 has a regulatory role in the production of proinflammatory cytokines by mast cells." (PMID 36169255, 2022).
Insulin resistance (1 paper, 2016). Increased resistance towards insulin, that is, diminished effectiveness of insulin in reducing blood glucose levels. "Whether the splicing misregulation of SOCS7 in DM contributes to insulin resistance remains to be tested." (PMID 27063795, 2016).
liver cancer (1 paper, 2024). An epithelial or non-epithelial malignant neoplasm that arises from the liver. "SOCS1 alterations through SOCS7 and CISH alterations were detected in liver cancer tissues at the following frequencies: SOCS1, 1.1%; SOCS2, 0.8%; SOCS3, 6%; SOCS4, 0.3%; SOCS5, 1.3%; SOCS6, 1.3%; SOCS7, 2.4%; and CISH, 2.7%." (PMID 39307915, 2024).
liver fibrosis (1 paper, 2021). "Functionally, miR-199a-5p inhibition decreased TGF-β1-induced hepatic fibrosis, and knockdown of SOCS7 decreased the effect of DZNep on collagen I and α-SMA expression in TGF-β1-activated HSCs." (PMID 34040893, 2021). "Taken together, these data demonstrated that DZNep could effectively suppress hepatic fibrosis through regulating miR-199a-5p/SOCS7 pathway." (PMID 34040893, 2021). "DZNep suppresses hepatic fibrosis through regulating miR-199a-5p/SOCS7 axis, suggesting that DZNep may represent a novel treatment for fibrosis." (PMID 34040893, 2021).
ovarian carcinoma (1 paper, 2022). A malignant neoplasm originating from the surface ovarian epithelium. "Moreover, a recent study also illustrated that SOCS7 expression was connected with poor prognosis in ovarian cancer patients, based on which we revealed the noticeable correlation between the expression of SOCS7 protein and survival rate or clinicopathological features of HGSOC patients." (PMID 35624501, 2022). "However, the function of SOCS7 in the pathogenesis of ovarian cancer, especially in HGSOC, is still unknown." (PMID 35624501, 2022). "Collectively, SOCS7 constrains the tumorigenicity of HGSOC, potentially through mediating HuR ubiquitination and minimizing its cellular level in ovarian cancer." (PMID 35624501, 2022). "The SOCS7 correlates with HGSOC and suppresses its tumorigenesis through regulating HuR and FOXM1, which also suggests that SOCS7 is a prospective biomarker for the clinical management of ovarian cancer, especially HGSOC." (PMID 35624501, 2022).
prostate carcinoma (1 paper, 2022). A carcinoma that arises from epithelial cells of the prostate gland. "The upregulation of SOCS7 was found to restrict the aggressive cellular activities of prostate cancer." (PMID 35624501, 2022).
psoriasis (1 paper, 2022). An autoimmune condition characterized by red, well-delineated plaques with silvery scales that are usually on the extensor surfaces and scalp. "Few studies in the literature have examined the interactions between SOCS3 and SOCS7 gene polymorphisms and immune diseases, and more studies are needed to elucidate the effect of SOCS on psoriasis because of the complex pathogenesis of this disease." (PMID 36169255, 2022). "The polymorphisms of SOCS3 rs4969169 and SOCS7 rs3748726 were found to have no effective role in the pathogenesis of psoriasis." (PMID 36169255, 2022).
type 2 diabetes (1 paper, 2013). "The objective of this study was to determine if variants in SOCS7 play a role in variation of glucose and insulin levels and the development of type 2 diabetes (T2DM)." (PMID 23767996, 2013). "As a result of SOCS7’s role in glucose homeostasis in mice, we hypothesized that variants in SOCS7 might contribute to variation in glucose and insulin levels as well as the development of Type 2 diabetes (T2DM) in humans." (PMID 23767996, 2013).
viral infection (1 paper, 2021). "Our data has shown that SOCS7 could exert a suppressive effect on IFN response, which may be conducive to viral infection." (PMID 34345210, 2021).